SEPTIN7 (septin 7)
Description:
Filament-forming cytoskeletal GTPase. Required for normal organization of the actin cytoskeleton. Required for normal progress through mitosis. Involved in cytokinesis. Required for normal association of CENPE with the kinetochore. Plays a role in ciliogenesis and collective cell movements. Forms a filamentous structure with SEPTIN12, SEPTIN6, SEPTIN2 and probably SEPTIN4 at the sperm annulus which is required for the structural integrity and motility of the sperm tail during postmeiotic differentiation.
Synonyms: CDC10; SEPT7; CDC3; SEPT7A; Septin-7; NBLA02942
Tractability: Small molecule: a structure with a bound ligand is known; it has a high-quality binding pocket. PROTAC: ubiquitination databases record sites on it.
Gene: Protein-coding gene on chromosome 7 (35,800,932 to 35,907,110, forward strand). Ensembl gene ENSG00000122545.
Subcellular location: Cytoplasm; Chromosome, centromere, kinetochore; Cytoplasm, cytoskeleton, spindle; Cleavage furrow; Midbody; Cytoplasm, cytoskeleton, cilium axoneme; Cell projection, cilium, flagellum
Subcellular location (Human Protein Atlas): Actin filaments; Cytokinetic bridge; Midbody; Primary cilium
Pathways (Reactome):
Signal Transduction: MAPK6/MAPK4 signaling
Gene Ontology:
Molecular function: cadherin binding; identical protein binding; protein binding; GTP binding; GTPase activity; molecular adaptor activity; structural molecule activity
Biological process: cytoskeleton organization; positive regulation of non-motile cilium assembly; cilium assembly; cytoskeleton-dependent cytokinesis; intracellular protein localization; regulation of embryonic cell shape
Cellular component: actin cytoskeleton; axoneme; cilium; extracellular exosome; midbody; non-motile cilium; nucleus; septin complex; sperm annulus; stress fiber; apical plasma membrane; cell division site; cytosol; microtubule cytoskeleton; septin ring; cleavage furrow; cytoplasm; cytoskeleton; motile cilium; spindle
Genetic constraint (gnomAD): Loss-of-function variants: 1 observed, 15.15 expected, observed/expected ratio (o/e) 0.066, 90% interval 0.022 to 0.31. The upper end of that interval is the gene's LOEUF score, 0.31, which puts it in group 1 of 6, group 1 being the genes least tolerant of losing a copy. Missense variants: 93 observed, 142.81 expected, observed/expected ratio (o/e) 0.65, 90% interval 0.55 to 0.77. Synonymous variants: 34 observed, 40.89 expected, observed/expected ratio (o/e) 0.83, 90% interval 0.63 to 1.11.
Homologues: Orthologues: chimpanzee SEPTIN7 (99% identical), macaque SEPTIN7 (99% identical), mouse Septin7 (99% identical), guinea pig SEPTIN7 (98% identical), pig SEPTIN7 (96% identical), rat Septin7 (96% identical), tropical clawed frog septin7 (95% identical), zebrafish septin7a (92% identical), dog SEPTIN7 (92% identical), rat AABR07033045.1 (75% identical), Drosophila melanogaster pnut (66% identical), Caenorhabditis elegans unc-59 (43% identical). Paralogues in human: SEPTIN2 (46% identical), SEPTIN5 (44% identical), SEPTIN8 (42% identical), SEPTIN1 (42% identical), SEPTIN10 (41% identical), SEPTIN11 (40% identical), SEPTIN14 (40% identical), SEPTIN6 (39% identical), SEPTIN9 (36% identical), SEPTIN3 (35% identical), SEPTIN12 (33% identical), TMEM250 (6% identical).